PFN1P2 (profilin 1 pseudogene 2)
Synonyms: COAS3; formerly C1orf152
Gene: Transcribed processed pseudogene on chromosome 1 (120,433,656 to 120,434,052, reverse strand). Ensembl gene ENSG00000270392.
Diseases named in the same sentence as PFN1P2 in open-access papers:
PFN1P2 is named in the same sentence as 1 disease in open-access papers, as found by Europe PMC text mining. Sharing a sentence is not in itself a finding about the gene and the disease. The quoted sentences say what the papers report.
COVID-19 (1 paper, 2025). A disease caused by infection with severe acute respiratory syndrome coronavirus 2. "AQP7P1 (FDR = 7.34 × 10−3), PFN1P2 (FDR = 1.61 × 10−2), AL590452.1, and LINC00842 (FDR < 0.05) were significantly associated with COVID-19 BIs." (PMID 40650217, 2025).